TNF (tumor necrosis factor)
Diseases named in the same sentence as TNF in open-access papers (continued):
Sharing a sentence is not in itself a finding about the gene and the disease.
COVID-19 (continued). "However, the data on the circulating levels of TNF-related biomarkers in COVID-19 patients are limited." (PMID 36219652, 2022). "In COVID-19, cytokine storms are triggered by the action of IFNγ, TNFα, IL-1, IL-2, and IL-6." (PMID 34436742, 2022). "However, the first problem found is the discrepancy in the TNF levels identified in COVID-19 by several groups; some authors showed that COVID-19 patients display increased levels of this cytokine, but others cannot find it." (PMID 35631442, 2022). "The rate of discontinuation of anti-TNF-α antibody agents was high after patients had COVID-19; however, we should consider that differences in administration intervals may have influenced the decision of the discontinuation of the agents." (PMID 35089397, 2022). "Interestingly, median expression level of TNF-α is significantly lower in recovered COVID-19 patients and vaccinated compared to healthy controls women." (PMID 35283772, 2022). "This suggests that antibodies targeting IL-6 and TNF-signalling may restore NK cell functions in COVID-19 patients." (PMID 35891232, 2022). "Despite definitive conclusions in this regard cannot be drawn, results of some studies seem to indicate that the protective effect of the TNF antagonists in IBD patients can be ascribed to the reduction of the hyper-inflammatory responses frequently found in the most severe COVID-19 cases." (PMID 35812420, 2022). "While anti-TNF therapies can mitigate detrimental outcomes in severe COVID-19 due to dampening of the systemic inflammatory response, the reduction of antibodies over time might necessitate considering booster doses in these patients." (PMID 35941646, 2022). "Impaired IFN-γ and TNF-α production may be due to soluble factors in plasma from COVID-19 patients, as shown by a study on NK cell activity in response to K562 cell stimulation." (PMID 35625739, 2022). "In addition, these results add to the growing evidence that supports further investigation of TNF inhibitors as a possible treatment in the early course of severe COVID-19." (PMID 36060521, 2022). "Simultaneously, KEGG enrichment analysis identified the possible signaling pathways for the effect of baicalin on CS, mainly including antifolate resistance, TNF signaling pathway, IL-17 signaling pathway, Coronavirus disease-COVID-19, and Neutrophil extracellular trap formation, etc.." (PMID 35350754, 2022). "TNF-α-induced ROS production could contribute to the spread of COVID-19 symptoms to distant tissues such as the brain." (PMID 36296527, 2022). "Moreover, anti-TNFα agents have been reported to control the multisystem inflammatory syndrome related to COVID-19." (PMID 36417106, 2022). "In addition, TNF-α was found at higher levels in the blood and diseased tissues of patients with severe COVID-19 and it was the critical cytokine in the occurrence of CS." (PMID 35350754, 2022). "On the contrary, TNF-α seems to have participated in the whole course of COVID-19 illness." (PMID 35237624, 2022). "Next, we investigated more deeply the interplay between IFNs and immune markers whose elevation in circulation has been associated with poor prognosis in COVID-19, including interlelukin (IL)-22, SAA, IL-10, IP-10, IL-6, IL-8, MIP-3α, IL-1RA, MIP-1α, TNF-α, MCP-1, and MCP-4 (39, 40, 43, –45)." (PMID 35217532, 2022). "PIBD patients on anti-TNFα need to remain vigilant about COVID-19 even after two vaccinations, and a third vaccination may be considered." (PMID 36298483, 2022). "When cytokine levels were evaluated in the culture media of PBMCs derived from healthy individuals and COVID-19 patients, a higher tendency to secrete cytokines such as IL-1b, TNF, IL-6, INFg, IL-17, MCP-1, and IL-10 was observed in cells exposed to SARS-COV2 infection." (PMID 35831294, 2022).
COVID-19 (continued). "This dysregulated response likely causes substantial tissue damage through cell death, both through type I IFN, which can kill via a variety of pathways and via IFNγ, which in synergy with TNF-α appears to play a detrimental role by inducing cell death during COVID-19." (PMID 35244141, 2022). "Furthermore, TNF-alpha is involved in key features of COVID-19 with poor outcome: elevated TNF-alpha levels have been associated with increased capillary leaking and the risk of thrombosis in ARDS and the action of neutrophils." (PMID 36060521, 2022). "Moreover, severe COVID-19 patients requiring intensive care in the hospital have high plasma IL-2, IL-7, IL-10, and TNF-α levels." (PMID 36035409, 2022). "In the BAL fluid of patients with COVID-19, significantly increased and extremely high levels of the cytokines IL-1β, IL-1RA, IL-17A, TNF-α, and G-CSF and the chemokines CCL7, CXCL1, CXCL8, CXCL11, and CXCL12α were found in comparison with BAL fluid of patients with influenza." (PMID 34793331, 2022). "However metformin has been found to reduce TNF-alpha, IL-6, and possibly boost IL-10 in females more than males, which is relevant to the pathophysiology of COVID-19." (PMID 36395143, 2022). "This coincided with TNF being considered as a therapeutic target for COVID-19." (PMID 35350754, 2022). "A large study at the Mount Sinai Institute of New York followed up with 1484 patients hospitalized for suspected or confirmed COVID-19 up to 41 days after admission: IL-6 and TNF-alpha at the time of hospitalization confirmed their predictive value on disease severity and death risk." (PMID 36422198, 2022). "Accordingly, we evaluated the levels of IL-17, IFN-γ, TNF-α, IL-10, IL-6, IL-4 and IL-2 in patients with clinical COVID-19 and long COVID-19, with cases classified as mild, moderate and severe, and associations with risk factors for sex, age and presence of comorbidities." (PMID 35846757, 2022). "TNF-α-blocking therapies have proved beneficial in patients with chronic inflammatory diseases and could therefore pose a new treatment option in COVID-19." (PMID 36056419, 2022). "Moreover, combined therapy and thiopurine monotherapy resulted in a significantly higher proportion of patients with severe COVID-19 compared to TNF-antagonist monotherapy (8.8% and 9.2% vs. 2.2%, respectively, p < 0.001)." (PMID 35448412, 2022). "In this regards, TNF-α-inhibiting capacity of natural carotenoids was investigated in terms of blocking TNF-α-hTNFR1 interaction in COVID-19 patients with the help of a combination of in silico approaches, based on virtual screening, molecular docking, and molecular dynamics (MD) simulation." (PMID 36574379, 2022). "Moreover, ROS production by TNF and LPS-primed neutrophils in response to formyl peptides was significantly lower in COVID-19 patients who died compared to survivors as well as in superinfected patients compared with non-superinfected patients." (PMID 35637483, 2022). "COVID-19 severity is associated with cytokine storm, which is the result of a sharp increase in levels of inflammatory mediators such as interleukin (IL)-2, IL-7, IL-10, G-CSF, IP10, MCP-1, MIP1A and TNFα." (PMID 34050887, 2022). "TNF-α showed a higher immunoreactivity in the COVID-19 group than in the control group (p < 0.001)." (PMID 34463916, 2022). "Moreover, it was revealed that there was a cytokine storm, including interleukin-1 (IL-1), IFN-γ, TNF-α, IL-6, and others, in patients with COVID-19." (PMID 36362417, 2022). "Similar results were also observed on tumor necrosis factor-α (TNF-α) levels in COVID-19 patients." (PMID 35215138, 2022). "Another hallmark of TNF and IFN-γ–shock or COVID-19 is lymphopenia and immunosuppression." (PMID 36419185, 2022). "The COVID-19 responsive inflammatory molecules, such as IL-6 and IL-8 and tumor necrosis factor-α may be beyond these changes." (PMID 35350852, 2022).
COVID-19 (continued). "Multiple studies suggest that excessive inflammatory production of proinflammatory cytokines such as IL-6 and TNF-α may trigger ARDS, which will accelerate disease progression and increase the risk of death in COVID-19 patients." (PMID 35450063, 2022). "Furthermore, severe COVID-19 is associated with excessive release of pro-inflammatory cytokines, such as IL-1, IL-6, IFN-γ, and TNF-α, which were shown to decrease the synthesis and secretion of apolipoproteins in hepatic cell lines in a dose-dependent manner." (PMID 35402531, 2022). "While most randomized trials in COVID-19 have focused in modulating the IL-1/IL-6 pathway, data from multiple studies suggest that anti-TNF treatments may also play a role in the therapeutic armamentarium." (PMID 36405747, 2022). "TNF-α is detected in the blood and tissues of patients with COVID-19." (PMID 35619180, 2022). "The chronic low-grade inflammation indicated by the increased percentage of elevated TNF-α and the elevated concentration of hsCRP in survivors of COVID-19 might partially explain the reduced FMD even nearly 1year after diagnosis." (PMID 35237624, 2022). "The results of bioinformatics analysis revealed that the mechanism of puerarin in COVID-19/COAD might be associated with NF-κB, MAPK, IL-17, TNF, and HIF-1 signaling pathway." (PMID 35677450, 2022). "Similarly, COVID-19 plasma exosomes from patients in both their early and late hospitalization stimulated the expression of IL-6, IL-8, and TNF-α in CD14+ monocytes." (PMID 36526691, 2022). "This may result in a smaller increase in the activity of COX2 and TNFα expression than would be expected in plasma from COVID-19 patients." (PMID 36233111, 2022). "TNF-α has proven to be an independent predictor of COVID-19 severity and mortality." (PMID 35548445, 2022). "Subjects with COVID-19 showed leucocytes and lymphocytopenia, as well as a systemic elevation of pyrogenic cytokines such as interleukin (IL)-6, IL-10, and tumor necrosis factor (TNF)-α." (PMID 36500994, 2022). "Severe COVID-19 disease is associated with a so-called “Cytokine Storm”, which is a dramatic increase in inflammatory cytokines/chemokines (especially IL-1β, IL-6, IL-8, and TNF-α) and other inflammatory factors that promote tissue injury and can predict the severity of COVID-19 and survival." (PMID 36296272, 2022). "Indeed, high serum levels of inflammatory cytokines such as interleukin-6 (IL-6), IL-8, and tumor necrosis factor-α (TNF-α) are observed in COVID-19 patients and predicted disease severity and poor outcome." (PMID 35075453, 2022). "COVID-19 triggers signaling cascades in response to viral contact, leading to the release of type I interferons, cytokines, and chemokines (IL-1β, IL-2, IL-6, IL-17, TNF-α, G-CSF, IFN-γ, CXCL10, CCL2 and CCL3, i.e., the cytokine storm)." (PMID 35982898, 2022). "It has been suggested that anti-TNF therapy might reduce inflammation-mediated vessel leakage in COVID-19, but this requires further study." (PMID 35782361, 2022). "It is unclear whether anti-TNF-α treatment improves or deteriorates COVID-19 patient outcomes, and this case demonstrates that infliximab can be used safely." (PMID 35089243, 2022). "Thus, antibody titers remain crucial for protecting against COVID-19, and PIBD patients on anti-TNFα whose antibody concentrations are low and decayed should pay more attention to COVID-19 after the initial vaccine series." (PMID 36298483, 2022). "On the basis of preconcentration analysis of cells, these subsets were mainly involved in the new crown pneumonia and inflammation pathways containing TNF signaling pathway, coronavirus of COVID-19, IL-17 signaling pathway, NK cell–mediated cytotoxicity, and TNF signaling pathway." (PMID 35911765, 2022). "The network pharmacology results showed that Yinqiao powder may inhibit the inflammatory response by suppressing IL-6, CXCL2, TNFα, NF-κB, etc., in the treatment of COVID-19." (PMID 36467981, 2022).
COVID-19 (continued). "In COVID-19, the viral envelope E protein triggers the activation of the NF-κB inflammatory signaling cascade and the interaction with inflammatory factors, such as tumor necrosis factor-alpha (TNF-α) and interleukin 6 (IL-6)." (PMID 35990630, 2022). "Reduction of TNF levels with the administration of effective anti-TNF preparations may significantly interfere with this phenomenon and reduce COVID-19 severity in IBD patients." (PMID 35812420, 2022). "The cytokine storm has already been attenuated following recovery from COVID-19, as levels of TNF-α, free active TGF-β, IFN-γ, IL-1β, IL-2, IL-4, IL-6, IL-8, IL-10, IL-12p70, IL-17 and MCP-1/CCL2 during convalescence were not higher compared to healthy volunteers." (PMID 35757700, 2022). "Additionally, COVID-19-induced cytokine storm syndrome often includes high IL-6 receptor, TNF-α, granulocyte-colony stimulating factor and other immune products." (PMID 35992174, 2022). "Inhibition of the TNF-α-NF-κB inflammatory pathway in COVID-19 patients may prevent pulmonary complications." (PMID 36366521, 2022). "Research based on the SECURE-IBD database also suggests that TNF antagonist treatment was not an independent risk factor for severe COVID-19 and plays a significant protective role." (PMID 35223745, 2022). "The authors concluded that high concentrations of PGRN may block TNFα-mediated inflammation in COVID-19 patients." (PMID 35453521, 2022). "An increase in serum levels of TNF-α has been correlated with the severity of COVID-19." (PMID 36363785, 2022). "Current recommendations are to use lower doses of prednisone (20 mg/d) or budesonide and to avoid thiopurines, methotrexate, and tofacitinib, and postpone anti-TNF therapies, ustekinumab, and vedolizumab for 2 weeks while monitoring the development of COVID-19." (PMID 35089243, 2022). "Therefore, although promising, these two mediators should be considered carefully as targets for COVID-19 therapy with anti-IL-6 and anti-TNF monoclonal antibodies." (PMID 35720401, 2022). "Relatively selective COX-2 inhibitors (e.g., celecoxib, etoricoxib) may reduce pro-inflammatory cytokine levels, as shown in mice with influenza A infection (TNF-α, G-CSF, and IL-6) and in hospitalized COVID-19 patients (IL-6)." (PMID 35530041, 2022). "We suggest that high production of TNF, TNFRSF13B, and IL32 might be associated with and serve as markers for COVID-19 severity-specific therapies." (PMID 35983322, 2022). "In COVID-19 patients, TNF-α and IFN-γ expression is reduced in CD4+ T cells; high levels of failure markers are expressed in CD8+ T cells; and programmed cell death protein-1 (PD-1) and T cell immunoglobulin structural domain and mucin structural domain-3 (TIM-3) expression are increased." (PMID 36091053, 2022). "This suggests that in COVID-19, methotrexate acts in the same direction as TNF inhibitors." (PMID 36389759, 2022). "TNF-α may therefore pose a promising target for the treatment of severe cases of COVID-19 exhibiting hyperinflammation." (PMID 36056419, 2022). "Interestingly, we noted that cytokines widely associated with COVID-19 severity such IL6, CXCL10, and TNF showed multiple but modest correlations with clinical parameters in all groups, likely reflecting their multifunctional role in disease development." (PMID 34957382, 2022). "The reason why COVID-19 patients presented lower levels of lymphocytes is still unclear, although some hypothesis suggested that COVID-19 increases levels of tumor necrosis factor-α and interleukin-6, which are closely correlated with lymphopenia." (PMID 35806866, 2022). "This cell-host interaction is important as many of the cytokines produced in response to COVID-19 (i.e., interleukin-1 beta (IL-1β), IL-2, IL-6, IL-8, IL-10, and tumor necrosis factor alpha (TNFα)) stimulate infiltration of macrophages, monocytes, and neutrophils into the lung tissue." (PMID 35033181, 2022).
COVID-19 (continued). "Molecular mimicry of SARS-CoV-2 and acetylcholine receptor and cytokine storm due to TNF-α, IFN-γ, IL-6, regulatory T cell (Th-17), and IL-17 is contributed to the ARDS in COVID-19 and myasthenic crisis and also associated with the severity, poor outcome, and the mortality." (PMID 35818475, 2022). "In COVID-19 patients, increased TNF-α concentration may provoke inflammatory cascade and induce the initiation of cytokine storm that may result in fatal pneumonia and acute respiratory distress syndrome (ADRS)." (PMID 36574379, 2022). "Increased plasma IL-6, TNF-α, and IL-1β are characteristic of severe COVID-19 patients." (PMID 36298628, 2022). "• The TNF-α-NF-κB axis is considered as a potential therapeutic target for COVID-19." (PMID 35422702, 2022). "Cuban patients infected with the SARS-CoV-2 virus had, although not dramatically, a higher chance of presenting COVID-19 symptoms when they were carrying the − 308.A allele of the TNFα gene." (PMID 37521833, 2022). "Supporting this possibility are previous findings indicating that high levels of TNF-alpha and IL-6 correlate negatively with T cell numbers in severe COVID-19 in the general population, and that B cell numbers and antibodies are reduced in COVID-19 patients with hematologic malignancies." (PMID 36700209, 2022). "Importantly, we found expression of IFN-γ and TNF-α in NK cells of most of COVID-19 patients, and some of the post-COVID-19 patients." (PMID 36275702, 2022). "A reasonable explanation could be the prior exposure to SARS-CoV-2, as TNF patients represent 70% (12/17) of the COVID-19 recovered group in RD patients, so the stronger cellular response is likely to be related to this fact." (PMID 35964130, 2022). "One of the hypothesis of the mechanism of action in COVID-19 is that high TNF-α levels may aggravate lymphophenia by killing lymphocytes." (PMID 36287942, 2022). "In addition, tramadol, as a strong analgesic, has also been reported to alleviate COVID-19 symptoms by reducing cytokine storm including TNF-α." (PMID 36146616, 2022). "SECURE-IBD and J-COSMOS data showed that IBD patients receiving corticosteroids and a combination of anti-TNFα antibody and immunosuppressive drugs at the time of diagnosing COVID-19 pneumonia had a higher severity rate of COVID-19 compared to patients receiving anti-TNFα antibody monotherapy." (PMID 36417106, 2022). "Furthermore, CCL2, IL-6, and TNF-α expressions were higher in COVID-19 patients compared to controls (P<0.001)." (PMID 35982898, 2022). "So, on a speculative plan, it is possible that the post-acute overexpression of VCAM-1 and IL-8 in poor sleepers could be somehow influenced by higher levels of pro-inflammatory cytokines (including IL-1 and TNF-α) during the acute phase of COVID-19." (PMID 36062000, 2022). "High levels of IL-1β, IL-6, and TNF-α in hyperinflammatory conditions, which are strong inducers of hyaluronidase, lead to the production and accumulation of HA in the alveolar spaces in severe COVID-19 patients." (PMID 35741101, 2022). "There was no apparent harmful association between anti-TNF treatment and severe COVID-19, ICU admission, or death." (PMID 36498812, 2022). "In addition, the most significant KEGG pathways were enriched for overlapping DEGs in COVID-19 patients, including human immunodeficiency virus 1 infection, apoptosis, the mTOR signaling pathway and TNF signaling pathway." (PMID 35755819, 2022). "Corresponding factor inhibitors (TNF-α inhibitors and IL-17 inhibitors) may also play a role in the treatment of COVID-19, achieving the treatment strategy of “new use of old drugs” and “homotherapy for heteropathy”." (PMID 35935817, 2022). "COVID-19 symptoms rapidly become critical 7–10 days after onset, which is associated with an increase in acute-phase response markers, including CRP and ferritin, and inflammatory cytokines, including IL-6, IL-2, and TNF-α." (PMID 34436742, 2022).